RNA5SP527 (RNA, 5S ribosomal pseudogene 527)
Gene: Ribosomal RNA gene on chromosome 4 (67,439,992 to 67,440,118, forward strand). Ensembl gene ENSG00000274759.
Homologues: Orthologues: chimpanzee 5S_rRNA (91% identical), guinea pig 5S_rRNA (51% identical). Paralogues in human: RNA5SP525 (46% identical), RNA5SP443 (44% identical), RNA5SP536 (43% identical), RNA5SP194 (42% identical), RNA5S1 (41% identical), RNA5S10 (41% identical), RNA5S11 (41% identical), RNA5S12 (41% identical), RNA5S13 (41% identical), RNA5S14 (41% identical), RNA5S15 (41% identical), RNA5S16 (41% identical), and 24 more.